TLR5 (toll like receptor 5)
Diseases named in the same sentence as TLR5 in open-access papers (continued):
Sharing a sentence is not in itself a finding about the gene and the disease.
tumor (continued). "Our recent studies indicate that the dominant negative R392X TLR5 polymorphism determines the nature of tumor-promoting inflammation in the presence of a tumor at sterile (extra-mucosal) locations." (PMID 25897427, 2015). "Altogether, these results show that 131I-anti-TLR5 mAb is capable of detecting lesions in a TLR5-expressing tumor, with high target selectivity, and may offer a promising agent for hepatocarcinoma diagnosis and encourage further investigation." (PMID 24932259, 2014). "In addition, elevated expression of MAP1S in response to flagellin feed-back regulated tumor inflammatory microenvironment in the late stages of TLR5 signaling through degradation of MyD88 in autophagy process." (PMID 24466264, 2014). "It was found that H22 cells and H22-xenografted tumor tissue exhibited higher levels of TLR5 expression than normal liver tissue, indicating that TLR5 may be a novel biomarker of hepatocarcinoma, although the mechanisms underlying remain far from understood." (PMID 24932259, 2014). "As both CD11b+ and CD11c+ cells are capable of antigen presentation and production of pro-inflammatory cytokines that can drive cytotoxic immune responses, it is likely that these cells are the bridge between TLR5-mediated stimulation and cytotoxic eradication of tumor cells." (PMID 24454895, 2014). "The biodistribution data showed that 131I-anti-TLR5 mAb had a high tumor uptake and T/NT ratio." (PMID 24932259, 2014). "By contrast, flagellin-induced TLR5 activation mediates tumor regression." (PMID 24371445, 2013). "Moreover, TLR5 activation has been reported to induce the expression of the autophagy-associated protein MAP1S, thereby promoting autophagic activity that reinforces tumor suppression." (PMID 40497049, 2025). "This is likely due to the more immediate innate-oriented immune response that becomes triggered upon activation of TLR5 with flagellin-C inserted in this virus, which led to tumor section samples where the immune cells may have already left the tumor by the time they were analyzed." (PMID 38787254, 2024). "Furthermore, TLR5 agonist promoted the activation and tumor infiltration of CD8+ T cells." (PMID 38630304, 2024). "Similarly, TLR5-dependent interaction with the commensal gut microbiota accelerates carcinogenesis at anatomically distant sites through tumor-promoting systemic inflammation and by attracting MDSCs and immunosuppressive γδ T cells into the tumor microenvironment." (PMID 37555952, 2023). "As TLR1/2, TLR2/6, TLR4 and TLR5 are the most prominently expressed surface TLRs on NK cells, we investigated whether the co-activation of FcγRs with these TLRs would enhance the cytotoxic activity of NK cells, resulting in improved tumor cell killing." (PMID 34681717, 2021). "Indeed, it was shown recently that in an animal model of keratinocyte skin cancer due to chronic inflammation, tumor formation was dependent on bacterial infection and was specifically driven by flagellin (the ligand for TLR-5), whereas antibiotic treatment inhibited tumor formation." (PMID 32111012, 2020). "We hypothesized that the TLR5 agonist flagellin, which is a stable protein being resilient to physicochemical insults, will potentiate peptide vaccines and survive physicochemically hostile tumor microenvironment induced by PDT." (PMID 33171765, 2020). "We addressed the question of whether TLR5 ligation ameliorates the in vitro efficacy of αCD40CMV and αCD40mNPM1 by evaluating these molecules based on their binding specificity, DC maturation and induction of viral- and tumor-specific T cell responses." (PMID 33281829, 2020). "Furthermore, ex vivo tumour TLR5 expression was proved through immunohistochemistry staining." (PMID 31576678, 2019). "Additionally, early images showed the TLR5− 4T1 tumors were larger than TLR5+ 4T1 tumors, which suggested that TLR5 expression might inhibit tumor growth in vivo." (PMID 31852883, 2019).
tumor (continued). "The tumour-inhibitory effect of ablating TNFR or MyD88 in radiosensitive leukocytes in InvEE mice was greater than that of TLR-5 ablation (0.01<P<0.05; one-way analysis of variance), suggesting that additional components of the immune system that converge on NF-κB may contribute." (PMID 25575023, 2015). "Interestingly, we did not observe significance differences in SFB between TLR5-deficient and wild-type mice, despite the fact that they exhibit significantly higher serum levels of IL-17, at least in the presence of a tumor." (PMID 25897427, 2015). "However, the underlying mechanism by which TLR5 signaling inhibits cancer cell proliferation and tumor growth has not been elucidated." (PMID 24466264, 2014). "In prostate cancer, activation of TLR2, TLR4, and TLR9 stimulates tumor growth while activation of TLR3, TLR4, TLR5, and TLR7 suppress tumor development." (PMID 41601666, 2026). "Toll-like receptor 5 (TLR-5) signaling and hypoxia within the pre-metastatic niche are responsible for the upregulation of interleukin-6 (IL-6) and tumor-promoting inflammation." (PMID 40002869, 2025). "Activation of TLR5 induces the secretion of proinflammatory cytokines such as IL-8 and TNF-α, which subsequently suppresses tumor cell proliferation and migration." (PMID 40497049, 2025). "For instance, an attenuated Salmonella typhimurium strain engineered to secrete Vibrio vulnificus flagellin B (FlaB) in tumor tissues can activate both TLR4 and TLR5." (PMID 38523155, 2024). "The activation of TLR-2 and TLR-9 by PCa cells appears to promote tumour growth; conversely, the activation of TLR-3, TLR-5, and TLR-7 has been suggested as a potential way to prevent PCa." (PMID 39201739, 2024). "We assessed the efficacy of TLR5 agonist and anti-PD-1 combination therapy in inhibiting tumor growth using the B16F10 tumor model." (PMID 38630304, 2024). "Flow cytometry of isolated tumor-infiltrating immune cells and splenocytes showed a notable increase in granzyme B within CD8+ T cells in both the TLR5 agonist monotherapy and combination therapy groups." (PMID 38630304, 2024). "Our findings suggest that the use of an appropriate combination of CAR133 with the immune regulatory factor TLR5 agonist, CBLB502, enhanced the anti-tumor potential of NK92 cells in coordination with the mobilization of tumor-reactive endogenous immune cells." (PMID 37731205, 2023). "Among all TLR2, TLR4, and TLR5 subgroups and the positive TLR7 subgroup, patients with a low CD3–CD8 tumor–stroma index exhibited a worse survival." (PMID 36649244, 2023). "Among patients with a high TLR5 expression, five-year DSS was 81.8% (95% CI 65.7–97.9) among those with a CD3–CD8 tumor–stroma index of 4, falling to 50.3% (95% CI 31.9–68.7; p < 0.001, log-rank test) among patients with the lowest CD3–CD8 tumor–stroma index." (PMID 36649244, 2023). "SOSTDC1, TLR5, MT1G, and MUC6 were downregulated in locally advanced tumor tissue samples, whereas COL8A1 and THBS2 were upregulated (P<0.05)." (PMID 36969001, 2023). "TLR5 and TLR7 have significant anti-tumor effects through dendritic cell-mediated cytotoxic T cells activation and regulatory T cell (Treg) inhibition." (PMID 35680568, 2022). "The immunoadjuvant toll-like receptor 5 (TLR5), Entolimod, which has already been used in clinical practice, can exert anti-metastatic effects and keep immune memory in CT26 tumor cell induced CRC model through the NK-DC-CD8+ T-cell axis." (PMID 33262461, 2021). "Moreover, both 4T1 TLR5+ and 4T1 TLR5− tumors displayed obvious fluorescence signals, which indicated that fluorescence tag could be used for co-location of 4T1 tumor." (PMID 34336694, 2021).
tumor (continued). "The T/NT ratio (tumor/opposite muscle) was 1.4681 and 1.11254 for TLR5+ and TLR5− tumor, respectively (P < 0.01)." (PMID 34336694, 2021). "Immunohistochemical staining suggested that the expression of TLR5 was lower, whereas the expression of VEGFR, CD31, and MVD (microvessel density) was higher in TLR5− tumor-bearing mice." (PMID 34336694, 2021). "The expression of TLR5 expression was decreased, whereas VEGFR expression increased in TLR5− tumor compared with those in TLR5+ tumor." (PMID 34336694, 2021). "The expression of TLR1, TLR3, TLR5, TLR6, TLR7, TLR8, and TLR10 show significantly decreasing trends from normal tissues to surrounding tumor tissues and to tumor tissues." (PMID 34141706, 2021). "Toll-like receptor 5 (TLR5) controls endogenous immune responses to pathogens and is a promising target for pharmacological stimulation of anti-tumor immunity." (PMID 32292576, 2020). "The same tendency was seen in TLR5 expression, which was strong in 58% of the EBV/HPV-negative tumours, strong (29%) or mild (52%) in the HPV-positive tumours, and negative in 55% of the EBV-positive cases." (PMID 31238894, 2019). "In our whole population-based study of NPC in Finland, we examined the expression of TLR1, TLR2, TLR4, TLR5, TLR7, and TLR9 in 150 tumours and analysed their pattern of expression according to EBV and HPV status, and clinical outcome." (PMID 31238894, 2019). "For example, TLR5 and TLR9 exhibit anti-tumoral properties by activating immune cells and having a direct cytotoxicity effects on tumor cells." (PMID 28632155, 2017). "The target tumor cells were added to BMDMs activated by the following TLR agonists; TLR1/2 agonist Pam3, TLR2/6 agonist LTA, TLR3 agonist poly(I:C), TLR5 agonist flagellin, TLR7 agonist CL264, and TLR9 agonist CpG." (PMID 29123526, 2017). "We compared activation of TLR5 and the NLRC4 inflammasome by these two flagellin fusion proteins, and the anti-tumor immunity of these proteins was evaluated using a mouse cancer model." (PMID 27063435, 2016). "In the late stage of TLR5-induced inflammation, elevated MAP1S negatively regulated the tumor microenvironment to inhibit inflammation and induced autophagy to suppress tumorigenesis." (PMID 24466264, 2014). "Based on this rationale, the TLR5 agonist CBLB502 was administered and shown to promote tumor clearance in C57BL/6 and BALB/c mice." (PMID 24454895, 2014). "A novel set of experiments were performed integrating the activation of TLR5, NAIP5, and NLRC4 by bacterial flagellin into tumor immunotherapy." (PMID 24273542, 2013). "TLR5 is expressed in LNCaP and DU145 cells, and its activation induces the production of chemokines that recruit immune effector cells, including NK cells and cytotoxic CD8+ T cells, which are likely to contribute to tumor suppression." (PMID 41601666, 2026). "This bacterium can directly bind the butyric acid it produces to Toll-like receptor 5 (TLR5) on CD8+ T cells, activating the TLR5-dependent NF-κB pathway to enhance the function of cytotoxic CD8+ T cells, thereby exerting anti-tumor effects and enhancing the efficacy of anti-PD-1 therapy." (PMID 40370465, 2025). "VvFlaB-mediated TLR5 activation polarizes macrophages from the immunosuppressive M2 phenotype to the pro-inflammatory M1 phenotype, consequently enhancing CD8+ T cell infiltration and anti-tumour cytokine secretion." (PMID 40444793, 2025). "In a study by Yujie Sun and colleagues, it was shown that S. typhimurium engineered using Vibrio vulnificus (V. vulnificus) flagellin B (FlaB), which is a natural ligand of Toll-like receptor 5 (TLR5), strongly inhibits tumor growth and is an excellent aid for cancer immunotherapy." (PMID 38495751, 2024). "Downregulation of TLR5 in TNBC promoted vascular endothelial growth factor receptor expression and angiogenesis, leading to the proliferation of TNBC cells through the TRAF6 and SOX2 pathways to increase tumor aggressiveness and EMT expression." (PMID 38685971, 2024).
tumor (continued). "We hypothesized that TLR5 agonists’ activation of innate immune cells might prime CD8+ T cells and promote their migration and tumor infiltration, subsequently enhancing the efficiency of immune checkpoint inhibitors." (PMID 38630304, 2024). "While the total CD8+ population remained unchanged with TLR5 agonist monotherapy and combination therapy, the activated CD8+ T cell subset expressing cytokine IFN-γ increased significantly in both TLR agonist-treated groups, in both the tumor and spleen." (PMID 38630304, 2024). "The absence of an effect of TLR5 agonist treatment in TLR5 knockout mice underscores the specificity of direct TLR5 activation by TLR5 agonists in tumor suppression." (PMID 38630304, 2024). "To delve deeper into the effect of TLR5 agonist treatment on macrophage function, particularly the activation of T cell immune responses, we examined the co-stimulatory molecules CD40 and CD80 on macrophages from the tumor and spleen." (PMID 38630304, 2024). "We hypothesized that activation of innate immune cells by TLR5 agonists might enhance the effectiveness of immune checkpoint inhibitors by stimulating CD8+ T cell activation and promoting tumor infiltration." (PMID 38630304, 2024). "TLR5 agonists promote a shift from M2-like macrophages to M1-like macrophages and activate CD8+ T cells, suggesting their potential to enhance the effectiveness of PD-1 inhibitors in mouse tumor models." (PMID 38630304, 2024). "There is a growing body of preclinical evidence that agonists targeting TLR3, TLR5, TLR7/8, or TLR9 in combination with RT may lead to enhanced anti-tumor immunity." (PMID 37112730, 2023). "A low TLR5 immunoexpression associated and correlated with negative intratumoral CD3T and CD8T levels, low stromal CD3S and CD8S levels, and a low CD3–CD8 tumor–stroma index." (PMID 36649244, 2023). "In breast cancer, the TLR5 agonist activates the intrinsic signaling pathway leading to the upregulation of IFN-γ and IL-4 population and lowering of the proportion of regulatory T cells that results in cell proliferation and suppressing the tumor growth." (PMID 37822929, 2023). "Thus, combination treatment with TLR5 agonists and ICT enhanced survival in vivo from two independent ICT-refractory tumor models." (PMID 36635337, 2023). "M1 macrophage-derived exosomal lncRNA-HOTTIP and M2 macrophage-derived exosomal lncRNA-AFAP1-AS1 affect tumor metastasis by modulating the miR-26a/ATF2 axis and miR-19a/b-3p/TLR5/NF-κB signaling pathway, respectively, which provides a potential strategy for tumor immunotherapy." (PMID 36601121, 2022). "Similarly, intra-tumoral bacteria have been shown to stimulate TLR2 and TLR5 in PDAC TME, thus polarizing macrophages towards an M2 phenotype and consequently inducing a tumor-permissive Th2 phenotype." (PMID 33708214, 2021). "The adenovirus Ad5-vector-based vaccine Mobilan was developed for intra-tumoural delivery with the intention to extend the application of TLR5-targeting anticancer immunotherapy to tumours that do not naturally express TLR5." (PMID 33499143, 2021). "TLR5 agonists can be used as efficient antitumor vaccine without the need to identify tumor-specific antigens." (PMID 34178645, 2021). "This specificity is presumably due to the fact that, unlike normal cells, most tumor cells are characterized by constitutive activation of NF-κB and therefore cannot benefit from additional activation of NF-κB pathway upon TLR5 activation." (PMID 32027657, 2020). "However, our data revealed suppression of TLR5, TLR7, TLR8 and TLR10 in PBMCs from CRC patients, suggesting a possible flip in the expression of those receptors between the tumor and periphery which warrants further investigation." (PMID 31835892, 2019). "125I‐IgG failed to target TLR5 accurately in tumour‐bearing mice, exhibiting non‐specific retention in tumours." (PMID 31576678, 2019).
tumor (continued). "The exact effects of TLR-mediation on tumour growth are not known, but several in vitro studies on other types of carcinomas have shown that activation of TLR5 can promote tumorigenesis." (PMID 31238894, 2019). "The 4T1 tumors on the right and left flanks were transfected with lentivirus-TLR5 knockdown and negative-control Lentivirus, respectively, and the 4T1 tumor on the back was not transfected." (PMID 31852883, 2019). "Furthermore, to confirm that tumor fluorescence was GFP-tagged, transfected, virus-derived, and TLR5-specific, we inoculated mice with three types of tumors cells." (PMID 31852883, 2019). "The 4T1 tumours on left side was transfected by lentivirus‐TLR5 knock‐down, 4T1 tumour on right side was transfected with negative control lentivirus and on the back one was lentivirus‐non‐treated 4T1 tumour." (PMID 31576678, 2019). "In our whole population-based study, we retrieved 150 Finnish NPC cases and studied their tumour samples for TLR1, TLR2, TLR4, TLR5, TLR7, and TLR9 expressions by immunohistochemistry, and for the presence of EBV and high-risk HPVs with EBV RNA and HPV E6/E7 mRNA in situ hybridizations." (PMID 31238894, 2019). "Block group and 125I‐IgG group showed no obvious tumour image at any time‐point, which suggested the specific accumulation of 125I‐anti‐TLR5 mAb in TLR5‐positive tumour." (PMID 31576678, 2019). "The results showed that TLR4 KO mice had exacerbated tumor development, similar to those seen in mice that were not treated with Salmonella Typhimurium; on the other hand, TLR5 KO mice showed a partial decrease in tumor growth." (PMID 30302344, 2018). "To confirm whether the results of cell culture reflected in vivo conditions, we measured TLR5, IRAK-1, and IRAK-4 gene expression in tumor tissue induced by MKN45cl85 and 85As2 cells." (PMID 30410674, 2018). "Wound closure rates were similar in TLR-5−/− and control BM chimeras, suggesting that the dynamics of wound closure does not affect wound-induced tumour formation." (PMID 25575023, 2015). "We further show that TLR-5 plays a role in upregulation of the alarmin HMGB1 (High Mobility Group Box 1) in wound-induced mouse tumours and demonstrate that HMGB1 is also elevated in tumours of RDEB patients." (PMID 25575023, 2015). "The tumour-protective effect of TLR-5−/− BM was also apparent in non-wounded DMBA/TPA-treated mice, albeit less marked." (PMID 25575023, 2015). "This has been shown for subcutaneously growing TLR5-positive tumors as well as tumors growing in TLR5-positive tissues (e.g., liver) regardless of the TLR5 status of the tumor cells." (PMID 24583651, 2014). "TLR5 mRNA expression in the SCC tumor center showed the largest magnitude difference and was 30.8±22.9-fold higher (p<0.05) than in normal skin and also significantly higher than in the tumor center of BCCs (0.92±0.46, p<0.01)." (PMID 22808251, 2012). "In a mice model, the combined administration of Vibrio vulnificus Flagellin B and Human papillomavirus (HPV) E6/E7-derived peptides has shown an effective anti-tumor response by T-cells activation, which seemed to be independent of the TLR5 expression on the tumor cell surface." (PMID 36903639, 2023). "In summary, CAR133-NK92 cells armed with the TLR5 agonist, CBLB502, confer a new ability to mobilize immune cells and mediate an anti-tumor response to tumors that escape killing by CAR133-NK92 cells, which helps prevent tumor escape from CAR-T/NK cell immunotherapy." (PMID 37731205, 2023). "The 125I-antiTLR5 mAb could not target TLR5+ 4T1 tumor in group of pre-injecting unlabeled anti-TLR5 mAb, and tumors were not visualized by radiography, thus, confirming the specificity of 125I-antiTLR5 mAb imaging." (PMID 31852883, 2019). "In block group with unlabelled anti‐TLR5 antibody pre‐treatment, 125I‐antiTLR5 mAb failed to target TLR5 in tumour‐bearing mice, no tumour radio image could be obtained, which revealed the specificity of the 125I‐antiTLR5 mAb imaging." (PMID 31576678, 2019).